ABCC1 (ATP binding cassette subfamily C member 1 (ABCC1 blood group))
Diseases named in the same sentence as ABCC1 in open-access papers (continued):
Sharing a sentence is not in itself a finding about the gene and the disease.
ovarian carcinoma (continued). "One research group has described using an ABCC1 small molecule inhibitor in combination with a glutathione-depleting drug to explore cellular viability and chemosensitization in SKOV3 ovarian cancer cells where combination treatment displayed a loss of viability." (PMID 36551731, 2022). "Furthermore, ABCC1 is associated with higher tumor grade, and ABCC4 with reduced progression-free survival of patients with ovarian cancer." (PMID 28674494, 2017). "Oxaliplatin resistant ovarian cancer cells have been shown to overexpress ABCC1 and ABCC4." (PMID 24124770, 2013). "Efflux of payloads by ATP-binding cassette (ABC) transporters such as ABCB1 (P-glycoprotein) and ABCC1 (MRP1) is another resistance mechanism, particularly in chemotherapy-pretreated ovarian cancers." (PMID 41357243, 2025). "For example, increased expressions of ABCC1 and ABCG2 reduced the therapeutic effect in an ovarian cancer cell line." (PMID 39457707, 2024). "In ovarian cancer cells overexpressing ABCC1, CBD treatment can increase the intracellular accumulation of two ABCC1 substrates, Fluo3 and vincristine." (PMID 38068944, 2023). "The ABC protein family also includes MRP1 (ABCC1) and MRP2 (ABCC2) proteins, the level of which was statistically significantly downregulated by millepachine in cisplatin-resistant human ovarian cancer cells, known for the upregulation of these proteins." (PMID 34073042, 2021). "The drug-resistance-related genes ABCB1, ABCC1 GSK3A, had significantly higher expression levels in OCICs than in primary ovarian cancer cells." (PMID 25369529, 2014). "Our data supports a role for ABCB3, ABCC1, ABCC2, and ABCC3 in ovarian cancer chemoresistance, which is in agreement with previous studies." (PMID 24124770, 2013). "Higher gene expression of ABCC1 and ABCC3 was also found in ovarian cancer patients with unfavourable outcome following debulking surgery and platinum based chemotherapy." (PMID 24124770, 2013). "Our results show that HA induces chemoresistance against CBP, and increases the expression of the ABC transporters, ABCB3, ABCC1, ABCC2, and ABCC3 in ovarian cancer cell lines expressing the HA receptor, CD44." (PMID 24124770, 2013). "Overexpression of ABCC1 and ABCC2 in human ovarian cancer cells conferred marked resistance to chemotherapeutics, such as methotrexate." (PMID 24124770, 2013). "Indeed, previous studies showed that suppression of IGF-1R decreases ABCC2 expression and promoted drug sensitivity in human colon cancer cells, and that IGF-1 increased the expression of ABCC1, ABCC2, and ABCC3 in both leukemia cells and ovarian cancer cells." (PMID 33291663, 2020). "In agreement with the situation in research on other solid tumors (e.g., ovarian cancer), it may be concluded that single genes and protein products as ABCB1, ABCC1, and ABCG2 connected with chemoresistance are well characterized also in EC." (PMID 29543757, 2018). "Furthermore HA treatment significantly increased the expression of ABC drug transporters (ABCB3, ABCC1, ABCC2, and ABCC3), but only in ovarian cancer cells expressing CD44." (PMID 24124770, 2013). "Furthermore, increased expression of ABCC1 was observed in ovarian cancers from chemotherapy non-responders." (PMID 24124770, 2013).
hepatocellular carcinoma (31 papers, 2014 to 2025). A malignant tumor that arises from hepatocytes. "Upregulation of ABCC1 has been shown to be associated with more aggressiveness in hepatocellular carcinoma." (PMID 27171227, 2016). "However, downregulation of miR-363 was associated with ABCC1 overexpression in oxoplatin hepatocellular carcinoma cell lines." (PMID 32283808, 2020). "In functional in vitro studies, the HNF1A rs1169288C p.L27 polymorphism could significantly increase the ABCC1 promoter activity in human HepG2 hepatocellular carcinoma cell line and HEK293 kidney cells." (PMID 29066969, 2017). "Similar to the ceRNA network, NR2F1-AS1 was upregulated in oxaliplatin-resistant hepatocellular carcinoma patients and promoted ABCC1 expression by targeting miR-363 to increase chemoresistance." (PMID 35592674, 2022). "Conclusively, KCNQ1OT1 similarly exerted positive effect in the treatment of oxaliplatin resistance in liver cancer via miR-7-5p/ ABCC1 axis, offering a unique strategy for the hepatocellular cancer therapy." (PMID 35193115, 2022). "NR2F1-AS1 targets SOX1 via sponging miR-363 to regulate the progression of endometrial cancer and induces oxaliplatin resistance through miR-363 to target ABCC1 in hepatocellular carcinoma." (PMID 34408977, 2021). "ABCB1 and ABCG2 were mainly expressed in well-differentiated hepatoma cells, whereas poorly differentiated hepatoma cells expressed ABCC1 and ABCB2 (TAP1), accompanied by aberrant activation of the Hh signaling." (PMID 33440657, 2021). "The study conducted by Ma and colleagues demonstrated the key roles played by miR-133a and miR-326 in conferring adriamycin chemoresistance properties to the HepG2 hepatocellular carcinoma cell line model, through their regulatory effects on the ABCC1 gene." (PMID 25973145, 2015). "Based on the report from Huang’s group, NR2F1-AS1, the expression of which in oxaliplatin-resistant tissues was augmented, could target ABCC1 by sponging miR-363 and confer resistance to hepatocellular carcinoma." (PMID 36230565, 2022). "Particularly, circFoxo3 expression was increased in adriamycin-resistant hepatocellular carcinoma tissues and cell lines, and its overexpression enhances hepatocellular carcinoma invasion and growth via the miR-199a-5p/ATP Binding Cassette Subfamily C Member 1 (ABCC1) axis." (PMID 35205613, 2022). "Importantly, our data overlap with the report on the modulation of oxaliplatin resistance in hepatocellular carcinoma through the miR-7-5p/ABCC1 axis." (PMID 32708846, 2020). "It has been reported that miR-326 and miR-133a reduce adriamycin resistance of human hepatoma HepG2 cells through downregulating ABCC1 expression; miR-1291 could modulate cellular drug disposition through direct targeting ABCC1 in PANC-1 cells." (PMID 27487127, 2016). "CircPTGR1 and ABCC1 levels are significantly overexpressed in hepatocellular carcinoma (HCC) cells, and circPTGR1 modulates the 5-FU resistance of HCC cells via the miR-129-5p/ABCC1 axis." (PMID 35070998, 2021). "Our group has shown that GH elevates the specific ABC transporters, such as ABCC1, ABCC2, ABCB1, and ABCG2 in melanoma, hepatocellular carcinoma, and pancreatic cancer." (PMID 39123364, 2024). "Data from different human hepatocellular carcinoma (HCC) cohorts showed that both SPHK1 and the S1P exporter ABCC1 were expressed at higher levels in aggressive HCC when compared with normal liver or cirrhotic tissue." (PMID 35163211, 2022). "In particular, as prognostic indicators, ABCC1 and NFS1 have also been included in the survival prediction model of hepatocellular carcinoma, implying their robust roles in survival prediction." (PMID 34276794, 2021). "We have demonstrated that Hh transcription factors GLI1/2 were able to bind to the consensus sequence in the promoter of ABCC1 or ABCB2 to facilitate resistance to sorafenib, doxorubicin and cisplatin in poorly differentiated hepatoma cells." (PMID 33440657, 2021).
hepatocellular carcinoma (continued). "Suppression of GLI1/2 by RNA interference approaches or GANT61, a GLI inhibitor, resulted in a decrease in expression of ABCC1 or ABCB2, and partially restored the chemosensitivity in these poorly differentiated hepatoma cells." (PMID 33440657, 2021). "Both miR-133a and miR-326 can reduce the expression of ABCCl in the hepatoma cell line HepG2 and enhance the sensitivity of the cells to Dox, suggesting that miR-133a and miR-326 mediate MDR through modulating ABCC1." (PMID 32695666, 2020). "The rat hepatoma cell lines, col500 and col1000, we used in these studies were selected by colchicine, which is a substrate both for ABCB1 and ABCC1." (PMID 24409311, 2014). "Moreover, USP22 directly interacts with sirtuin 1 (SIRT1) and positively regulates SIRT1 protein expression, leading to activation of the SIRT1/AKT/ABCC1 pathway and MDR of hepatocellular carcinoma." (PMID 36694209, 2023). "Notably, upregulation of USP22 increases ABCC1 expression and subsequently contributes to sorafenib resistance in hepatocellular carcinoma (HCC) cells, suggesting that USP22 may serve as a therapeutic target for surmounting sorafenib resistance." (PMID 36694209, 2023). "In hepatocellular carcinoma, MDR is mediated by ABCB1, ABCB5, ABCC1, ABCC2, and ABCG2." (PMID 36557005, 2022). "Activation of GLI target genes, such as ABCC1 and TAP1, is responsible for drug resistance in hepatoma cells, with a CD133−/EpCAM− surface molecular profile, and GLI1 and truncated GLI1 account for the metastatic feature of the hepatoma cells, with upregulation of matrix metalloproteinases." (PMID 33440657, 2021).
colorectal cancer (25 papers, 2016 to 2026). A primary or metastatic malignant neoplasm that affects the colon or rectum. "This study identifies synthetic acridine-based chalcone analog 1C as an inhibitor of the ABCB1 transporter and suppressor of ABCC1 protein expression in colorectal cancer cells." (PMID 40362377, 2025). "The up-regulation of circRNA-ABCC1 (circ-ABCC1) contributes to the colorectal cancer cell stemness, spheroid formation, and metastasis of CD133− colorectal cancer cells." (PMID 39980929, 2025). "ABCA5 and ABCA8 were lowly expressed in cancer tissues, and ABCC1 was highly expressed in colorectal cancer tissues." (PMID 35783152, 2022). "Furthermore, circCD44 promotes oxaliplatin resistance in colorectal cancer cells by sponging miR‐330‐5p to upregulate ABCC1 expression." (PMID 40008841, 2025). "The expression of methyltransferase-like 3 (METTL3) is increased through SUMO1 SUMOylation modification in colorectal cancer, and increased METTL3 promotes the expression of ABCC1 protein, thus leading to drug resistance of colorectal cancer cells to chemotherapy." (PMID 37777749, 2023). "Mechanistically, circ-ABCC1 induces β-catenin to enhance colorectal cancer progression." (PMID 35765040, 2022). "The exosomal circ-ABCC1 is overexpressed in colorectal cancer and promotes stemness and invasion." (PMID 35765040, 2022). "Interestingly, a recent study showed that exosomes from CD133+ cells carrying circ-ABCC1 mediate cell stemness and metastasis in colorectal cancer, revealing that circ-ABCC1 may be used as a biomarker in CRC studies." (PMID 32528957, 2020). "ABCB1, ABCC1, and ABCC2 mRNA levels were compared between Caco-2 cells and other colorectal cancer cell lines (HCT-15, LoVo, DLD-1, HCT-116, SW620)." (PMID 41557172, 2026). "According to the mRNA expression levels of ABCB1, ABCC1, and ABCG2 transporters in colorectal cancer patients, there is a significant difference in the expression levels of these ABC transporters." (PMID 41557172, 2026). "The interaction between β-catenin and circ-ABCC1 can activate WNT/β-catenin and promote the progression of colorectal cancer." (PMID 39980929, 2025). "OX@Se-MnP NPs reversed MDR in colorectal cancer by down-regulating the expression of MDR-related ABC (ATP binding cassette) transporters proteins (e.g., ABCB1, ABCC1 and ABCG2)." (PMID 36859296, 2023). "ABCC1 and FMN2 were host genes of exosomal circRNA that were differentially expressed by more than two-fold in colorectal cancer." (PMID 34249673, 2021). "Moreover, ABCC1 is the most frequently overexpressed ABC transporter in the clinical tissue specimens of NSCLC and colorectal carcinoma." (PMID 36559089, 2022). "In colorectal cancer, ANRIL could sponge miR-Let-7a to enhance the expression of ATP binding cassette subfamily C member 1 (ABCC1), which promotes cholesterol efflux and inhibits inflammation in vivo." (PMID 32082313, 2020). "In addition, it will be interesting to observe the outcomes of the phase III clinical trial that is currently recruiting colorectal cancer-suffering patients (NCT04607421) and is going to evaluate the combination of encorafenib with ABCC1 substrates (irinotecan, 5-fluorouracil)." (PMID 36559089, 2022).
glioma (21 papers, 2013 to 2025). A benign or malignant brain and spinal cord tumor that arises from glial cells (astrocytes, oligodendrocytes, ependymal cells). "Considering only the patients who were treated with TMZ, higher ABCC1 also associated with a significant reduction in survival, suggesting a potential role of ABCC1 in glioma drug resistance." (PMID 35803910, 2022). "Multidrug resistant protein 1 (MRP1), encoded by the ABCC1 gene, is suggested to contribute to the chemoresistance of adult human gliomas." (PMID 23637844, 2013). "Finally, high ABCC1 expression was associated with tumor severity and worse patient outcomes both in primary and recurrent glioma." (PMID 35803910, 2022). "Furthermore, we found that NRF2 positively correlates with ABCC1 expression in tumor tissues of glioma patients, which can be associated with tumor aggressiveness, drug resistance, and poor overall survival." (PMID 35803910, 2022). "Sixty glioma-associated targets were associated with CHR, such as MDR transporters (ABCB1, ABCC1, ABCG2), cyclin-dependent kinases (CDK1, CDK6), matrix metalloproteinases (MMP2, MMP9, MMP12), and genes related to inflammation or oxidative stress (NOS2, NOX4)." (PMID 40963691, 2025). "Altogether, these results indicate that high ABCC1 expression is related to higher tumor aggressiveness, chemotherapy resistance, and poorer overall survival in glioma, indicating an interesting scenario for ferroptosis induction." (PMID 35803910, 2022). "Multivariate analysis indicated that higher ABCC1 was an independent prognostic factor for inferior OS in glioma (HR = 1.10, CI = 1.06–1.14), along with WHO grade and diagnosis age (all p < 0.05)." (PMID 35803910, 2022). "Kaplan-Meier curves with the CGGA, TCGA, and REMBRANDT datasets showed that glioma patients with higher levels of ABCC1 had a significantly shorter overall survival (OS) compared with patients with lower ABCC1 levels." (PMID 35803910, 2022). "Our analyses revealed higher levels of ABCC1 in glioblastoma patients compared to other glioma types (oligodendroglioma and astrocytoma)." (PMID 35803910, 2022). "In the CGGA cohort of patients, for instance, we observed a 5-year OS of 18% versus 68% for primary glioma patients with higher ABCC1 expression versus lower ABBC1 expression, respectively (p < 0.0001)." (PMID 35803910, 2022). "We carried out a rescue experiment to confirm the sensitizing role of miR-9-5p/ABCC1 axis on glioma TMZ." (PMID 34532283, 2021). "Then, we detected the tumor tissues of glioma patients, and concluded that ABCC1 was enhanced in tumor tissues of patients, and correlation analysis revealed that ABCC1 had a correlation with miR-9-5p." (PMID 34532283, 2021). "Among such transporters overexpressed in the BBB and glioma tumor cells are the P-glycoprotein multidrug resistance protein 1 (P-gp/MDR1/ABCB1) and the multidrug resistance-associated protein (MRP/ABCC1)." (PMID 33680961, 2021). "More biological and clinical studies are necessary to evaluate the utility of targeting the LINC00470/miR‐134/MYC/ABCC1 axis for the treatment of gliomas." (PMID 32916774, 2020). "Our study clarified the new mechanism by which LINC00470 acts as a ceRNA to sponge miR‐134, thereby regulating downstream molecules such as MYC and ABCC1 to maintain the malignant phenotype of glioma." (PMID 32916774, 2020). "Above all, increasing evidence shows that the overexpression of ABCC1 in glioma cells enhances drug resistance." (PMID 32916774, 2020). "We concluded that LINC00470 promoted the expression of MYC and ABCC1 by suppressing miR‐134, thus promoting glioma cell proliferation and invasion, and attenuating TMZ chemosensitivity." (PMID 32916774, 2020). "ABCC1/MRP1 overexpression has been observed in several types of glioma, including GBMs, GBMs with an oligodendroglial component (GBMO), anaplastic astrocytomas (grade III), and meningiomas." (PMID 31878061, 2019).